TRAJ17 (T cell receptor alpha joining 17)
Gene: T-cell receptor joining (J) gene on chromosome 14 (22,526,844 to 22,526,906, forward strand). Ensembl gene ENSG00000211872.
Diseases named in the same sentence as TRAJ17 in open-access papers:
TRAJ17 is named in the same sentence as 3 diseases in open-access papers, as found by Europe PMC text mining. Sharing a sentence is not in itself a finding about the gene and the disease. The quoted sentences say what the papers report.
atherosclerosis (1 paper, 2025). A disease characterized by the build-up of fatty material and calcium deposition in the arterial wall resulting in partial or complete occlusion of the arterial lumen. "Trav13‐2 [S29] and Traj17 [S30] were linked to primary Sjögren's syndrome and atherosclerosis, respectively." (PMID 40665793, 2025).
sarcopenia (1 paper, 2024). Progressive decline in muscle mass due to aging which results in decreased functional capacity of muscles. "Our study investigated the plasma proteome of individuals with age-related sarcopenia and identified 8 DEPs that showed promising predictive performance, including IGFBP2, PON3, LRG1, PRDX6, PTGDS, CD163, PRG4, and TRAJ17." (PMID 39725826, 2024).
TRAJ17 also shares sentences with these, for which no sentence is quoted: primary Sjögren's syndrome (1 paper).